ALDH1A1 (aldehyde dehydrogenase 1 family member A1)
Diseases named in the same sentence as ALDH1A1 in open-access papers (continued):
Sharing a sentence is not in itself a finding about the gene and the disease.
breast carcinoma (continued). "They found that ALDH1A1 decreased the intracellular pH in breast cancer cells, in order to promote the phosphorylation of TAK1, activate the NFκB signal pathway, and increase the secretion of GM-CSF, and this led to myeloid-derived suppressor cell expansion and immunosuppression." (PMID 35814382, 2022). "Limonin, quercetin, and curcumin inhibit breast cancer stem cells by downregulating ALDH1A1." (PMID 36387165, 2022). "made a breakthrough in research regarding the mechanism by which ALDH1A1 initiates breast cancer." (PMID 35814382, 2022). "Furthermore, the co-expression analysis showed that LDHA was negatively correlated with the expression of ALDH1A1 but positively correlated with the expression of CD44 in human breast cancer samples based on the TCGA data set." (PMID 34178639, 2021). "Hence, we propose that a dual reporter including one of the pluripotency markers (phOCT4-EGFP/NANOG-GFP/SORE6-GFP/SOX2 SRR2-pGreen fire) and ALDH1A1-DsRed2 can efficiently mark all the heterogeneous CSCs, at least in breast cancer." (PMID 34150761, 2021). "Associations between ALDH1A1 expression and molecular subtypes across human cancers were also identified, and a signature of increasing ALDH1A1 levels tended to be observed in all kinds of breast carcinoma, indicating the universal therapy-responsive role of ALDH1A1 in achieving better outcomes." (PMID 34545132, 2021). "Human U87MG glioblastoma and human HCT116 colorectal cancer are labelled as ALDH1A3+ cell lines, HEK293T as ALDH1A2+ cell line, human foetal astrocytes (hASTRO) and CCD-18Co human colon fibroblasts as ALDH1A1+ cell line and 4T1 mammary carcinoma as triple negative ALDH1A subfamily." (PMID 33478031, 2021). "Moreover, knockdown of ALDH1A1 in a TNBC cell line (MDA-MB-468) sensitized breast cancer cells to paclitaxel, doxorubicin and radiation therapy." (PMID 33919109, 2021). "Indeed, increased ALDH1A1 expression in relapsing tumors of human breast cancer after surgery and tamoxifen treatment has been observed." (PMID 35582039, 2020). "It has been hypothesized that the ALDH1 isoform ALDH1A1 is responsible for the metastatic property in breast cancer cells with high ALDH activity." (PMID 32423137, 2020). "Moreover, PKCλ correlated with ALDH1A1 and ALDH1A3 in basal-like breast cancer (ALDH1A1; p = 0.017; ALDH1A3; p = 0.016, χ2-test)." (PMID 32658903, 2020). "Various authors reported the prognostic value of ALDH1A1 in breast cancer patients." (PMID 35582039, 2020). "Finally, overlapping results have been obtained in human breast cancer cells, in which the expression of ALDH1A1 was involved in the regulation of adhesion, migration, and colony formation and in the acquisition of metastatic phenotype." (PMID 35582039, 2020). "Our analysis of ALDH1 isotypes showed a low expression of ALDH1A1 in breast cancer cell lines." (PMID 32423137, 2020). "Moreover, anchorage-independent growth and invasion were significantly reduced also in breast cancer cell lines with clear mesenchymal phenotype; with high expression of ALDH1A1, (MDA-MB-468 and SKBR3) after AKT2 silencing." (PMID 31357505, 2019). "Alternatively, ALDH1A1 may have other substrates that are involved in breast cancer cell growth, which could be identified through a broad high-throughput substrate screen." (PMID 31208996, 2019). "Although different breast cancer cell lines such as 184A1, SUM149, SUM159, and HCC1954 treated with RA presented a decrease in mammosphere formation, the breast cancer MCF-7 cell line responds to RA with an increase of stemness through an ALDH1A1-retinoic acid-HIF-1α-VEGF pathway." (PMID 31590252, 2019). "The exact molecular mechanisms through which ALDH1A1 selectively regulates growth in breast cancer cells is unclear, but could involve FOXM1 and Notch signaling." (PMID 31208996, 2019). "Alternatively, ALDH1A1 conversion of retinaldehydes to RA could serve to enhance breast cancer proliferation." (PMID 31208996, 2019).
breast carcinoma (continued). "Furthermore, in breast cancer patients, ALDH1A1+ cancer cells were enriched in metastatic lesions after tamoxifen treatment." (PMID 29393296, 2018). "The aim of the present study has been to assess whether ALDH1A1 controls the output of angiogenic factors in breast cancer cells and regulates tumor angiogenesis in a panel of in vitro and in vivo models." (PMID 30541574, 2018). "In this work we determined whether ALDH1A1 in breast cancer cells was involved in the output of angiogenic factors and whether it might influence tumor angiogenesis in a number of in vitro and in vivo experimental settings." (PMID 30541574, 2018). "Interestingly, knockdown of ALDH1A1 in breast cancer cells reduced in vitro and in vivo breast cancer metastatic ability." (PMID 30308036, 2018). "Next, we determined whether the reduced expression and activity of ALDH1A1 in breast cancer cells might influence in vivo tumor angiogenesis." (PMID 30541574, 2018). "While this suggests that ALDH is an important player in breast cancer metastasis; the actual functional contribution of ALDH1 (in particular its isozymes ALDH1A1 and ALDH1A3) in breast cancer metastasis requires further elucidation, and this was the goal of the current study." (PMID 28937653, 2017). "In contrast, 468ALDH1A3low and 159ALDH1A3low cells were observed to be significantly more adherent and more migratory than respective control cells (p < 0.05), suggesting that adhesion and migration of human breast cancer cells is differentially influenced by ALDH1A1 versus ALDH1A3." (PMID 28937653, 2017). "In breast cancer cell lines, C/EBPβ-2 has been shown to regulate ALDH1A1 expression." (PMID 28148901, 2017). "To investigate the association of c-Met with CSC markers such as ALDH1A1, ALDH1A3, CD44, and CD133 at gene expression levels in human breast cancers, we analyzed mRNA data and the clinical information of 1904 patients of breast cancers from cBioPortal for Cancer Genomics." (PMID 28966724, 2017). "Furthermore, recent meta-analysis has also indicated that ALDH1A1 can serve as a predictor of poor prognosis in breast cancer patients." (PMID 27793013, 2017). "On the other hand, the role of ALDH1A1 in CSCs was demonstrated in that ALDH1 high cells from breast cancer isolated by Aldeflour assay were the tumor-initiating cells, indicating ALDH1A1 might drive tumor proliferation, differentiation, and maintenance." (PMID 26783961, 2016). "ALDH1A1 might be a major contributor to ALDH1 activity in breast cancer because only high expression of ALDH1A1 mRNA was found to be significantly correlated with poor overall survival in breast cancer patients." (PMID 26783961, 2016). "Considered together, these study findings are inconclusive in determining whether the expression of ALDH1A1, either as mRNA or as a protein, can predict clinical outcomes in breast cancer patients." (PMID 26462023, 2015). "ALDH1A1 has been suggested as a breast cancer stem cell marker." (PMID 26462023, 2015). "However, contradictory findings on the role of ALDH1A1 in predicting the prognosis of breast cancer patients have been reported." (PMID 26462023, 2015). "Several studies reported that ALDH1A1 expression in IHC could correlate with Ki67 expression (indicative of proliferation rate) in pancreas cancer and breast cancer." (PMID 26160842, 2015). "The results derived from overall analysis suggested that the overexpression of ALDH1A1 might be related to the enriched-HER2 subtype of breast cancer (ER-PR-HER2+), which is derived from the transformation of mammary late luminal progenitor cells." (PMID 24938375, 2014). "Both ALDH1A1 and ALDH1A3 have been associated with poor prognosis in breast cancer." (PMID 24887554, 2014). "Thus, we also want to know the relationship between ALDH1A1 expression and the three most important molecular markers of breast cancer, ER, PR, and HER2." (PMID 24938375, 2014).
breast carcinoma (continued). "Because the majority of breast cancers originate in the lobular part of the mammary ductal tree and only a small percentage originate in bigger ducts, this ALDH1A1+ cell population with stem/progenitor characteristics may be significant for cancer initiation." (PMID 24887554, 2014). "ALDH1A1+ breast cancer patients have poorer prognosis in all subcategory analysis." (PMID 24938375, 2014). "Therefore, we performed a systematic review and a meta-analysis to assess the robustness of the relationship between ALDH1A1 expression and clinicopathologic parameters/outcomes in breast cancer patients." (PMID 24938375, 2014). "ALDH1A1 expression might also be related to some basal-like breast cancers, which are derived from the transformation of mammary luminal progenitor cells." (PMID 24938375, 2014). "However, the prognostic value of ALDH1A1 for breast cancer remains controversial despite numerous independent studies." (PMID 24938375, 2014). "Additionally, recent studies in MCF-7 and other breast cancer cells have shown that MUC1-C increases ALDH1A1 expression, raising the possibility that MUC1-C induces ALDH1 activity and thereby mammosphere formation." (PMID 24770886, 2014). "However, ALDH1A3 expression has been shown to correlate better with aldehyde activity in breast cancer stem cells than ALDH1A1 expression, and correlate with tumor grade, stage and metastasis." (PMID 24053169, 2013). "Moreover, whether other claudin low TNBC cell lines or other breast cancer subtypes display similar heterogeneity in ALDH1A1 function remains to be determined." (PMID 40076923, 2025). "ALDH1A1 can regulate the pH in tumour cells, activate the production of phosphorylated TAK1, upregulate the NF‐κB signalling pathway and cause the expansion of MDSCs, thus forming an immunosuppressive microenvironment and inducing the malignant progression of breast cancer." (PMID 40665579, 2025). "However, high ALDH1A1 levels in breast cancer cells could similarly affect the CD24−CD44+ population." (PMID 39251846, 2024). "Research has shown that the induction of ALDH1A1 enzyme activity can promote the expansion of myeloid-derived suppressor cells and plays a role in triggering the pre-cancerous immune microenvironment, promoting breast cancer progression, and ultimately leading to tumor growth." (PMID 38138996, 2023). "A meta-analysis showed that ALDH1A1 could indicate a poor prognosis in women with breast cancer." (PMID 36120232, 2022). "Consequently, ALDH1A1 was the only ALDH1 isoenzyme that could be used as a maker to predict unfavorable survival in breast cancer patients." (PMID 36120232, 2022). "Moreover, ALDH1A1 contributed to CCR2-mediated breast cancer cell growth and invasion." (PMID 35173149, 2022). "hypothesized that ALDH1A1 was activated in the MDA-MB-468 breast cancer cell line, which stably expressed CYP2J2 and attenuated caspase-3/7 activity and the production of reactive oxygen species induced by cytotoxic agents, such as paclitaxel, doxorubicin, sorafenib, and staurosporin." (PMID 35814382, 2022). "Moreover, ALDH1A1 seems to play a role in the early differentiation of breast cancer stem cells." (PMID 36139578, 2022). "Furthermore, ALDH activity might be post-translational regulated by the NOTCH signaling pathway, through the induction of SIRT2 expression that deacetylates ALDH1A1 on Lys-353 residue and therefore promoting breast cancer tumorigenesis and growth." (PMID 35299840, 2022). "The aim of this study was to investigate Znhit1 and HIF-2α gene expression in breast cancer tissues as well as their relation to CSCs markers LGR5, ALDH1A1 and β-catenin in tissue and serum of BC patients." (PMID 35978075, 2022). "Similarly, although Aldefluor positivity was associated with breast CSCs, ALDH1A1 did not correlate with Aldefluor positivity and performed poorly as a predictor of breast carcinoma progression." (PMID 31941033, 2020).
breast carcinoma (continued). "Considering the conflicting nature of data regarding BCSC phenotypes, it is important to systematically investigate the expression of CD44, CD24 and ALDH1A1 in different breast cancer subtypes to understand whether the expression of these biomarkers indeed correlates with tumorigenic potential." (PMID 32423137, 2020). "Moreover, knockdown of ALDH1A1 sensitizes breast cancer cells to chemotherapy and radiation." (PMID 30308036, 2018). "Thus, targeted suppression of ALDH1A1 activity may help to sensitize breast cancer cells to traditional cancer therapy." (PMID 29433490, 2018). "In Du145 cells, the overexpression of HAPTOV1 also associated to significantly increased levels of stemness genes LIN28A, ALDH1A1 and MYC, whereas in PC3 cells it associated to a significant expression of LIN28A, MYC, NANOG and POU5F1 genes, in agreement with reports in breast cancer cells." (PMID 28938627, 2017). "It has been reported that ALDH1A1 expression could be a predictor of poor prognosis in a wide range of cancers such as ovarian carcinoma, lung cancer, breast cancer, esophageal squamous cell carcinoma, prostate cancer, papillary thyroid carcinoma, colorectal carcinoma and gastric cancer." (PMID 26160842, 2015). "If cancer stem cells, which presumably have a high mRNA expression level of ALDH1A1 and account for 3-4% of breast cancer cells, are the main source of elevated ALDH1A1 in tumor tissue, then the vast majority of ALDH1A1 mRNA measured in our study could still come from stromal cells." (PMID 26462023, 2015). "Some studies have shown that ALDH1A1 protein expression is associated with late-stage cancer, large tumor size, chemoresistance, and poor prognosis, while other studies have found that ALDH1A1 protein levels do not predict breast cancer survival." (PMID 26462023, 2015). "Our results suggest that the analysis of ALDH1A1 expression in breast cancer not only provides a better understanding of the relationship between breast tumorigenesis and cancer genomics but may also be beneficial for the design of treatment and the assessment of the prognosis of patients." (PMID 24938375, 2014). "A strong association was found between family history of breast cancer and a high frequency of Aldh1a1 expression in breast ductules in women, regardless of a hereditary breast-ovarian cancer syndrome status (Brca1 and Brca2 mutations), age, parity, or occurrence of cancer." (PMID 24594504, 2014). "Notably, breast cancer tissue strong for ALDH1A1 expression displayed weak NOTCH1 staining compared to ALDH1A1 weak tumor tissue (P = 0.002), and the relationship between ALDH1A1 and NOTCH1 mRNA positivity was significant (Pearson correlation - 0.337, P = 0.014; Spearman’s rho - 0.376, P = 0.006)." (PMID 23767668, 2013). "Conversely, in breast cancer stem cells (CSCs), SIRT2 was found to promote the activity of aldehyde dehydrogenase 1A1 (ALDH1A1) via deacetylation, which in turn facilitates breast CSCs activation and self‐renewal." (PMID 39215785, 2025). "We observed that breast cancer cell lines contain distinct populations that display ALDH-/low and ALDH1A1/bright phenotypes." (PMID 39513121, 2024). "A substantial positive correlation was observed between HSF1 and either ALDH1A1 (p = 0.0009) or CD44 (p < 0.0001) in breast cancer patients with high HER2 expression." (PMID 38646654, 2024). "We first investigated the expression of the oncoprotein c-Myc and four breast cancer stem cell (BCSC) biomarkers: CD44, CD24, CD133 and ALDH1A1." (PMID 37353799, 2023). "Citral, which is a natural product, shows potent inhibitory activity against ALDH1A1, ALDH1A3, and ALDH2 in breast cancer cells." (PMID 36694633, 2023). "In this research, we performed immunohistochemical (IHC) staining on sixty breast cancer surgical specimens for c-Myc, CD44, CD24, CD133 and ALDH1A1." (PMID 37353799, 2023).
breast carcinoma (continued). "Our analysis revealed significantly higher CSC-related stemness genes (OCT4, SOX2, NANOG) (p < 0.0001) and ALDH1A1 (p < 0.0001) in TNBC (GSE30682), in contrast to ER+ luminal breast cancer (GSE5460)." (PMID 38038865, 2023). "Altogether, these findings demonstrate the significance of ALDH1A1, ALDH1A3, and ALDH2 inhibition as potential therapeutic targets in breast cancer." (PMID 37686694, 2023). "In two clinical trials to eliminate the activity of breast cancer stem cells (BCSCs) with bevacizumab (VEGF inhibitor) (NCT01190345) or reparixin (CXCR1/2 inhibitor) (NCT01861054), ALDH1A1 is one of the markers to measure the effect of drugs on BCSC activity." (PMID 36694633, 2023). "In breast cancer cells, NFκB induced expression of CCAAT/enhancer-binding protein beta (C/EBPβ); the latter formed a complex with MUC1 to activate ALDH1A1 gene expression." (PMID 37298333, 2023). "Using an online RNA-seq database based on basal-like breast cancer patients, we found that TAB182 negatively correlated with ALDH1A1 at the gene expression level in basal-like breast cancer patients." (PMID 37953246, 2023). "In this study, KRT13 induced stem cell phenotypes in MCF7 breast cancer cells, and increased expression of stemness-related genes of CD44, c-Myc, ALDH1A1 and Nanog." (PMID 35078507, 2022). "Markers consistently altered at lower bufalin concentrations (20 nM) were C-Kit, the CSC marker ALDH1A1, and the EMT factor Slug, which has previously been shown to be a regulator of CD44+ CSCs in breast cancer." (PMID 36362141, 2022). "High levels of NIK expression increase breast cancer cell tumorigenicity and upregulate BCSC markers, such as aldehyde dehydrogenase 1 family, member A1 (ALDH1A1)." (PMID 35805056, 2022). "Although a study on breast cancer reported that NFRSF17 can act as a co-receptor of ALDH1A1, KLF4 and NANOG, mediating their tumour-promoting effects in breast cancer." (PMID 36203424, 2022). "Further analyses using the GEPIA2 and TIMER2.0 databases revealed that NOLC1 was positively correlated with stemness-related genes, including MYC, ALDH18A1, ALDH1A1, SMAD2, SMAD3, etc., in both all breast cancer and TNBC." (PMID 35174077, 2022). "Disruption of IFN-1 signalling (via non-functional mutation in the IFN1I receptor) in tumours arising in HER2/neu transgenic mice deregulated a number of genes, including aldehyde dehydrogenase-1A1 (ALDH1A1), the marker of breast cancer stem cells." (PMID 35625798, 2022). "The elimination of ALDH1A1, ALDH1A3 inhibits ALDH1 activity, increases chemosensitivity, and reverses chemoresistance in breast cancer." (PMID 36387165, 2022). "Aldehyde dehydrogenase 1 family member A1 (ALDH1A1) is a stemness marker and promotes the malignant behaviors in breast cancer." (PMID 34903206, 2021). "As expected, we found that GSK3β or PGK1 depletion using their siRNAs significantly induced ALDH1A1 expression, suggesting that both GSK3β and PGK1 negatively modulated the stemness of breast cancer cells." (PMID 34403222, 2021). "They found that ALDH1A1 and HTRA2 regulates CCR2‐mediated breast cancer cell growth and cellular invasion in a CCL2/CCR2 context‐dependent manner." (PMID 34708890, 2021). "Of note, IFNAR-neuT tumors specifically exhibited deregulation of genes having adverse prognostic value in breast cancer patients, including breast CSC marker aldehyde dehydrogenase-1A1 (ALDH1A1)." (PMID 33430520, 2021). "While these CD44high clusters showed a downregulation in stem cell markers ALDH1A1 and ABCG2, they did show an increase in ALDH2, a stem cell marker less common in breast cancer." (PMID 34579762, 2021). "Adipocyte-associated secretion of IL-6 also participates in the Notch/Wnt/TGF-β signaling pathways by upregulating ALDH1A1 and LEF1 and AXIN2 gene expression in the Wnt pathway to enhance the invasiveness, metastasis and angiogenesis of breast cancer." (PMID 34202411, 2021).